EGFR (epidermal growth factor receptor)
Diseases named in the same sentence as EGFR in open-access papers (continued):
Sharing a sentence is not in itself a finding about the gene and the disease.
cancer (continued). "Therefore, the nuclear localization of AKT, EGFR, and MDM2, and the exclusion of nuclear FOXO3a, have been linked with enhanced drug resistance, poor prognosis, and unfavorable overall survival in various cancers." (PMID 34445495, 2021). "Intriguingly, similar to DUSP proteins, some cancer cells, including glioblastoma, are dependent on Spry proteins for their growth by adaptation, which makes Spry proteins play an onco-promoting role contrary to their original role as a negative regulator of the EGFR-activated ERK signaling pathway." (PMID 34685488, 2021). "The hormone may engage in crosstalk with EGFR in modulating a variety of cancer cell activities." (PMID 33827580, 2021). "Conversely, NGS represents a broader approach that covers non-hotspot regions of the EGFR gene as well as mutations in other cancer-related genes which could be targeted or reveal specific mechanisms of resistance." (PMID 34006948, 2021). "The communication between Notch and EGFR signaling may lead to more aggressive disease due to acquired resistance to EGFR-targeted chemotherapeutics through enhanced EMT characteristics, a behavior often associated with cancer aggressiveness." (PMID 33681228, 2021). "Similarly, by utilizing Alexa 546 and DyLight 649 labeled antibodies, FRET/FLIM has been applied to determine Gefitinib phosphorylation statuses for modulating the stability of EGFR dimers, providing a novel method for cancer-targeted therapy to deregulate EGFR signaling." (PMID 34138374, 2021). "For example, cancer‐derived EVs deliver EGFR and integrin αv into liver stromal cells which could contribute to liver toxicity of anti‐EGFR ADCs and anti‐integrin αv ADCs." (PMID 33613875, 2021). "Since the EGFR pathway is also a main regulator of cell proliferation, we reasoned that the BrdU assay could be more suitable to detecting any possible effects of miR-16 on cancer cell proliferation." (PMID 34948154, 2021). "Furthermore, enhanced nuclear expression of STEAP3 promotes cancer cell proliferation by enhancing stemness phenotype and accelerating G1/S transition through regulating intracellular signaling and facilitating nuclear trafficking of EGFR." (PMID 34741044, 2021). "Hence, cinobufagin exerts selective anti-cancer effect toward EGFR-overexpressed cancer cells." (PMID 34925034, 2021). "Different sub-localizations of EGFR may exert different functions for cancer progression." (PMID 34830108, 2021). "Therefore, targeting autophagy may overcome resistance to anti-cancer drugs, including anti-EGFR and sorafenib as well as butyrate." (PMID 34829834, 2021). "Therefore, the use of ICI on tumors with a strong active signaling via EGFR might be less effective, given that the cancer cells impair, at least partially, the therapeutic effect of the activated CD8 T cells." (PMID 34211836, 2021). "Consequently, cancer cell proliferation was promoted through the EGFR/PI3K signaling pathway." (PMID 34069424, 2021). "Hence, EGFR expression in HPV-infected cancer may be regulated by multiple factors such as existing complex mechanisms and HPV viral protein." (PMID 34646755, 2021). "Therefore, our results support the hypothesis that LncRNAs are functional participants in therapy resistance/sensitivity to cancer drugs, and target‐gene therapies ‘EGFR/AKT/ERK/mTOR’." (PMID 33433063, 2021). "In the majority of OSCC cases, epidermal growth factor receptor (EGFR) association (EGFR / ErB1 / HER1) has been reported to encourage aggressiveness, metastases, poor prognosis and resistance to anticancer therapy.This is expressed in a variety of other cancers." (PMID 34393414, 2021). "However, for patients with EGFR mutation-positive cancer, it is recommended not to miss treatment by EGFR-TKI single agent." (PMID 34577852, 2021).
cancer (continued). "Therefore, it is noteworthy to investigate EGFR regulating mechanisms in a multiple-cancer type." (PMID 34646755, 2021). "Additionally, EGFR can be mutated in cancers to become constitutively active without ligand binding." (PMID 34887764, 2021). "Moreover, GPER appears to be required for stemness maintenance in cancer stem cells via PKA/Bcl-2 associated agonist of cell death (BAD) pathway and the development of chemoresistance via EGFR/ERK/Akt-mediated ATP Binding Cassette, Subfamily G, Member 2 (ABCG2) expression." (PMID 34831222, 2021). "Consequently, inhibition of EGFR leads to the inhibition of cancer cells." (PMID 33921332, 2021). "However, to determine how intrinsic and acquired resistance to EGFR inhibitors in cancer treatments can be avoided, it is essential to comprehensively elucidate the regulatory landscape of the ERBB family and the interaction and crosstalk between lncRNAs and ERBB-family members." (PMID 33446634, 2021). "However, a significant proportion of EGFR-positive tumors display inherent or acquired resistance to the treatment attributed to mutations in the components of the EGFR-dependent pathway (e.g., EGFR, K-/N-ras) or activation of alternative cancer-related pathways." (PMID 34521767, 2021). "Thus, the development of membrane therapy could provide a complementary tool against EGFR-driven cancer." (PMID 33515553, 2021). "Taken together, we believe that for targeted therapy of cancer, the expression level of the target antigen, and its status must not be overlooked, and it is time to get back to the target, which in the case anti-EGFR antibodies are the EGFR protein and its dimerisation partners." (PMID 33562755, 2021). "Therefore, the prediction of the structure of binding peptides with high affinity for the EGFRAPS might be a very promising approach for the design of therapeutic agents or ligands for the treatment of EGFR-overexpressing cancers." (PMID 33981532, 2021). "Therefore, YAP and TAZ may represent mechanistic therapeutic targets in combination with EGFR targeting therapy in order to prevent cancer cells from acquiring resistance and the consequent treatment failure." (PMID 34725466, 2021). "Although we provide a comprehensive bioinformatics analysis to determine the potential diagnostic genes between cancer and normal tissues, it may not be very accurate in evaluating EGFR-MT LUAD patients at every stage." (PMID 34868228, 2021). "In fact, KRAS-mutated cancer cells do not require EGFR activation." (PMID 33923200, 2021). "We found that the IC50 values of several anti-cancer drugs, including sapitinib (an EGFR inhibitor) and selumetinib (a MEK1/2 inhibitor), decreased in the high-TRPV4 group, indicating that patients exhibiting high TRPV4 expression levels may be relatively sensitive to these anti-cancer drugs." (PMID 34262942, 2021). "AKT knockdown could reduce the survival of cancer cells by regulating EGFR." (PMID 34755451, 2021). "The most likely basis for resistance to anti-EGFR therapy in cancer cells is constitutive activation of signaling pathways linked to EGFR and this may or may not be a function of constitutive EGFR activity." (PMID 33827580, 2021). "Moreover, EGFR can activate the PI3K/AKT pathway in human cancer." (PMID 34641576, 2021). "In addition to direct mutational and non-mutational activation of EGFR, crosstalk pathways linking active EGFRs and other routes involved in cancer progression have been the subject of numerous studies." (PMID 34206026, 2021). "Recent studies revealed that EGFR inhibition could trigger autophagy in cancers." (PMID 33960631, 2021). "Furthermore, detection for EGFR driver mutation is hindered by problems such as cancer heterogeneity and lack of cancer tissues." (PMID 33634138, 2021).
cancer (continued). "Moreover, upstream of both RAF and PI3′-kinase signaling are the large family of receptor tyrosine kinases, such as EGFR, MET, ROS, ALK, and NTRK, that are mutated in a wide range of different cancers and for which there are numerous FDA-approved drugs linked to predictive biomarkers." (PMID 34298710, 2021). "Therefore, novel agents having greater specificity for HER2 inhibition while excluding EGFR may overcome the resiliency of the HER2/HER3 pathway in HER2-activated cancers and improve the clinical response rates versus conventional HER2 TKIs." (PMID 33774767, 2021). "Moreover, some cancer-related SNPs at five loci, namely, TERT, butyrophilin-like 2, TP63, bromodomain PHD finger transcription factor, and high-mobility group box protein 1 were found to have significant impacts on EGFR-mutated LUAD." (PMID 33802737, 2021). "Furthermore, the efficacy of EGFR‐targeted therapeutics in EGFRhigh/EpCAMlow carcinomas showing high Slug expression and high ERK1/2 phosphorylation levels may profit from re‐evaluation." (PMID 33340247, 2021). "Therefore, EGFR-targeting agents entered the clinic in multiple cancer types, with mixed success." (PMID 33364187, 2020). "Several studies showed that EGFR mutation patterns in NSCLC primary lesions and metastases in various body locations are not consistent with that found in the BMs, possibly because of the specific events required for cancer cell migration to and survival in the brain." (PMID 32195178, 2020). "Therefore, a complete understanding of EGFR functions has important implications in cancer biology." (PMID 32377505, 2020). "We examined whether doxazosin sensitizes cancer cells to osimertinib, a third-generation EGFR-TKI." (PMID 32764319, 2020). "The main downstream signaling pathway of EGFR/HER2 includes the rat sarcoma (RAS)-RAF proto-oncogene serine/threonine protein kinase-mitogen-activated protein kinase kinase 1/2 (MEK1/2)-extracellular signal regulated kinase 1/2 (ERK1/2) pathway controlling cancer development and progression 5-7." (PMID 32398965, 2020). "However, since EGFR-TKIs act not only on cancer cells but also on normal cells, a variety of adverse reactions may occur." (PMID 32260143, 2020). "Interestingly, we found that mutations in this region of EGFR, BRAF, ERBB2, and MAP2K1 were mutually exclusive, which is consistent with a previous report that suggested one driver mutation is sufficient cancer initiation or development." (PMID 32757330, 2020). "As EGFR or growth signaling tyrosine receptor kinases are located in the cellular membrane, we hypothesized that TKIs, including crizotinib, participate in modifying the P-gp activity in the membranes of drug-resistant cancer cells." (PMID 32528877, 2020). "PEPD binding to EGFR may be a potential target in treatment of cancers with EGFR overexpression." (PMID 32824561, 2020). "Interestingly, cannabinoids have also been shown to transactivate other receptors, such as epidermal growth factor receptor (EGFR) and tropomyosin receptor kinase B, resulting in cancer cell proliferation, interneuron migration and cortical development, and corneal epithelial cell proliferation." (PMID 33080916, 2020). "Serum miRNA expression on pathological diagnosis variables was statistically significant with an increase in the expression of miR-34 as a predictive biomarker for the type of metastasis M1b (P=0.020), adenocarcinoma cancer cell types (P=0.009) and adenocarcinoma negative EGFR mutation (P=0.031)." (PMID 32283582, 2020). "Moreover the rate of residual growing cancer cells under/after EGFR TKI therapy that can support AICDA- mediated deamination may differ between various TKI, thereby leading to different frequencies of acquired T790M." (PMID 32397977, 2020). "Thus, combination of MTHFD2 inhibitor and growth factor inhibitors might be a promising therapeutic strategy for EGFR inhibitor-resistant cancers." (PMID 32411609, 2020).
cancer (continued). "Moreover, a statistically significant correlation was observed between AG + GG genotypes and higher cancer staging irrespective of the EGFR mutation status." (PMID 32937815, 2020). "Moreover, the amplification of circular DNA elements containing oncogenes (such as EGFR and c-Myc) could help cancer cells adapt more effectively to variable environmental stress by acquiring fate-enhancing advantages." (PMID 32928268, 2020). "In addition to resistance to EGFR-TKIs, MDM2 amplification was also confirmed to be associated with the insensitivity to radiotherapy and the hyperprogressive disease (HPD) associated with cancer immunotherapy." (PMID 32611363, 2020). "In this study, a new system is developed to detect and isolate single-cancer cells expressing the T790M-mutated epidermal growth factor receptor (EGFR) mRNA from multiple non-mutated cancer cells by combining single-cell microarray chips and peptide nucleic acid (PNA)-DNA probes." (PMID 32605095, 2020). "EGFR could form a complex with β-catenin and promotes the invasion and metastasis of cancer cells." (PMID 33276800, 2020). "Previous studies have found that GPCRs could cross-talk with EGFR in cancer cell lines." (PMID 32911654, 2020). "Aberrant activation of EGFR stimulates several intracellular signaling pathways—Phosphoinositide 3-kinase (PI3K)/AKT, RAS/RAF/MEK/ERK, Src/signal transducer and activator of transcription (STAT)—Which in turn cause augmented cell proliferation and other oncogenic characteristics in cancers." (PMID 32756527, 2020). "We will continue to pursue whether EGFR disturbs cancer cell cholesterol homeostasis by down-regulating cholesterol efflux through this new signal pathway, so as to have a more comprehensive understanding of the effect of EGFR on the metabolism of cholesterol in cancer cells." (PMID 33224867, 2020). "The fact that COX2 c.-899G>C, EGF c.382A>G, and EGFR c.1562G>A polymorphisms were not directly associated with cancer risk is not surprising, considering that most of these polymorphic variants are low penetrance risk factors that have a minor influence in protein expression or function." (PMID 32338278, 2020). "Consequently, it is an urgent goal to discover new structural EGFR inhibitors for cancer therapy." (PMID 31967481, 2020). "Direct sequencing of EGFR polymerase chain reaction (PCR) products is a common approach for EGFR-mutation testing; however, its clinical usefulness is reduced by false-negative results due to the small proportion of cancer cells in collected samples available for DNA extraction." (PMID 33196648, 2020). "Parallel to this, icotinib in combination with BDMC caused marked decrease of EGFR activity through depressing Sp1 and the interaction of Sp1 and HDAC1/HDCA2, consequently diminishing protein and mRNA expressions of HDAC1/HDCA2 which are the key regulators for cancer development and growth." (PMID 32226300, 2020). "Unlike many cancers that originate from gain-of-function mutations in OGs such as EGFR and RAS, ccRCC manifests with prevalent loss-of-function mutations in TSGs, making the development of predictive biomarkers for individual targeted therapies and/or immunotherapies extremely challenging." (PMID 32743344, 2020). "Accordingly, inhibiting EGFR may affect EMT and inhibit cancer cell migration, although the association between EGFR and EMT is not as apparent as it is for PODXL." (PMID 32587323, 2020).
cancer (continued). "Therefore, it might be useful to adjust the ratio of M1/M2 macrophages for the treatment of EGFR-TKI-resistant cancer cells." (PMID 32256661, 2020). "Based on previously published Alu-element genome instability algorithms, we propose a molecular mechanism to explain how this non-coding region of DNA may be interacting with and impacting the stability of the EGFR gene and potentially generating this cancer-driver gene." (PMID 31940362, 2020). "Therefore, we speculate that TGF-β1 may increase EGFR-TKI resistance by regulating IRX4-induced cancer stem-like properties." (PMID 32820157, 2020). "The inhibition of EGFR activity may likewise support effects to curb cancer drug resistance." (PMID 32545311, 2020). "The ERBB family includes four distinct types of transmembrane tyrosine kinase receptors (EGFR, HER-2, HER-3 and HER-4), which are responsible for the establishment of several intracellular signaling pathways associated with normal cellular function and cancer cell development." (PMID 33066388, 2020). "The meta-analysis and systematic meta-analysis revealed that the EGFR R521K variation is not related to cancer risk, regarding various anticancer therapies may require further studies." (PMID 33680380, 2020). "Moreover, EGFR kinases inhibitors used as cancer therapy such as Erlotinib, Lapatinib and monoclonal antibodies targeting the extracellular domain of EGFR including Cetuximab were shown to improve psoriatic lesions in cancer patients." (PMID 33613525, 2020). "Thus, the work to elucidate the cancer heterogeneity that impacts remission to EGFR-TKIs could be crucial to develop new therapeutic strategies with better efficacy for LUAD patients with EGFR-activating mutations." (PMID 33123465, 2020). "Using the CRISPR/Cas9 system, we generated isogenic cell lines with EGFR/KRAS co-mutations from the KRAS-mutated A549 cell line, and demonstrated that these co-mutated cell lines were more susceptible to EGFR-TKIs, but not to conventional anti-cancer drugs, than parental cells." (PMID 32130260, 2020). "Previously, it has been shown the EGFR inhibitors lapatinib (EGFR), erlotinib (EGFR), afatinib (ErbB1, 2 and 4), gefitinib (EGFR) and dacomitinib (ErbB1-4), all of which have a quinazoline scaffold like sapitinib, are orally efficacious for the treatment of certain types of human cancers." (PMID 33163405, 2020). "Moreover, cell growth was restored in EGFR-overexpressing BASP1-knockdown cancer cells." (PMID 33042262, 2020). "Interestingly, in non-basal and TKI resistant cancer cells (J82), inhibition of EGFR phosphorylation mediated by erlotinib was associated with increased mRNA expression of EGFR (FC: 44.6), ERBB3 (FC: 92.3) and EREG (FC: 3.5)." (PMID 32978523, 2020). "Taken together, these findings support the conclusion that EGFR mutation status is a critical factor in determining prognostic potential of CEAIn and CEAPd in patients under EGFR-TKI treatment, and CEAIn and CEAPd are associated with distinct cancer progression profiles." (PMID 32034239, 2020). "The relationship between EGFR signalling and modulation of the immune response prompted us to investigate how EGFR inhibition therapy could affect an important player in the immune response to cancer, the complement system." (PMID 32054454, 2020). "Therefore, we supposed that EGF/EGFR signal may be critical in regulating PD-L1 expression in many cancers." (PMID 33324209, 2020). "Furthermore, integration of the HH and epidermal growth factor receptor (EGFR) signaling pathways regulates neural stem cell maintenance, homeostasis, and cancer development via HH–EGFR signaling, leading to specific GLI target gene expression (described in the following section)." (PMID 32859041, 2020). "EGFR and its ligands were found to associate in particular with two EV-relevant tetraspanins, CD9 and CD82, which act as regulators and integrators of its signalling, but might also contribute to its enrichment in EVs derived from cancer cells." (PMID 33302515, 2020).